SCFD1 (sec1 family domain containing 1)
Description:
Plays a role in SNARE-pin assembly and Golgi-to-ER retrograde transport via its interaction with COG4. Involved in vesicular transport between the endoplasmic reticulum and the Golgi (By similarity).
Synonyms: Sly1p; C14orf163; KIAA0917; STXBP1L2; RA410; SLY1
Tractability: Antibody: UniProt places it where antibodies can reach, with medium confidence. PROTAC: ubiquitination databases record sites on it; its protein half-life has been measured.
Gene: Protein-coding gene on chromosome 14 (30,622,291 to 30,737,694, forward strand). Ensembl gene ENSG00000092108.
Subcellular location: Cytoplasm; Endoplasmic reticulum membrane; Golgi apparatus, Golgi stack membrane
Pathways (Reactome):
Signal Transduction: RHOA GTPase cycle
Vesicle-mediated transport: COPII-mediated vesicle transport
Gene Ontology:
Molecular function: protein binding; protein-containing complex binding; syntaxin binding
Biological process: negative regulation of autophagosome assembly; regulation of protein transport; response to toxic substance; endoplasmic reticulum to Golgi vesicle-mediated transport; post-Golgi vesicle-mediated transport; regulation of ER to Golgi vesicle-mediated transport; retrograde vesicle-mediated transport, Golgi to endoplasmic reticulum; vesicle-mediated transport
Cellular component: cis-Golgi network; cytosol; Golgi membrane; Golgi-associated vesicle; cytoplasm; endoplasmic reticulum membrane; Golgi cisterna membrane
Genetic constraint (gnomAD): Loss-of-function variants: 7 observed, 16.25 expected, observed/expected ratio (o/e) 0.43, 90% interval 0.24 to 0.81. The upper end of that interval is the gene's LOEUF score, 0.81, which puts it in group 3 of 6, group 1 being the genes least tolerant of losing a copy. Missense variants: 152 observed, 170.7 expected, observed/expected ratio (o/e) 0.89, 90% interval 0.78 to 1.02. Synonymous variants: 71 observed, 57.84 expected, observed/expected ratio (o/e) 1.23, 90% interval 1.01 to 1.5.
Homologues: Orthologues: chimpanzee SCFD1 (100% identical), macaque SCFD1 (99% identical), dog SCFD1 (98% identical), pig SCFD1 (97% identical), mouse Scfd1 (96% identical), rat Scfd1 (95% identical), rabbit SCFD1 (94% identical), tropical clawed frog scfd1 (89% identical), guinea pig SCFD1 (88% identical), zebrafish scfd1 (87% identical), Drosophila melanogaster Slh (57% identical), Caenorhabditis elegans sly-1 (48% identical). Paralogues in human: STXBP2 (21% identical), STXBP3 (19% identical), VPS45 (19% identical), SCFD2 (16% identical), VPS33A (14% identical), VPS33B (13% identical).
Diseases named in the same sentence as SCFD1 in open-access papers:
SCFD1 is named in the same sentence as 19 diseases in open-access papers, as found by Europe PMC text mining. Sharing a sentence is not in itself a finding about the gene and the disease. The quoted sentences say what the papers report.
amyotrophic lateral sclerosis (5 papers, 2021 to 2025). Amyotrophic lateral sclerosis (ALS) is a neurodegenerative disease characterized by progressive muscular paralysis reflecting degeneration of motor neurons in the primary motor cortex, corticospinal tracts, brainstem and spinal cord. "For instance, expression levels of G2E3 and SCFD1 not only appear to causally effect the risk for amyotrophic lateral sclerosis but also attention deficient disorder, albeit with alternative directionalities." (PMID 33417599, 2021). "Interestingly, SCFD1 is considered an amyotrophic lateral sclerosis risk factor, and its down-regulation is related to motor dysfunction in Drosophila." (PMID 41009783, 2025). "SCFD1 has been proven to be closely associated with the pathogenesis of Parkinson’s disease and amyotrophic lateral sclerosis (ALS)." (PMID 37894929, 2023). "Moreover, we identified Wald ratio effects between four genes (IQCB, TTC34, MPV17L2 and SLC30A7) and multiple sclerosis risk, and effects between two genes (SCFD1, G2E3) and amyotrophic lateral sclerosis risk." (PMID 33417599, 2021).
pancreatic cancer (1 paper, 2025). "Among the previously known and here confirmed interactors (CDH1, DISP1, SCFD1, USE1, TSG101, and USP8), CDH1 (E‐cadherin), a critical adhesion molecule, is frequently lost or downregulated in pancreatic cancer, promoting epithelial‐to‐mesenchymal transition (EMT) and enhancing tumor invasiveness." (PMID 40952239, 2025).
tumor (3 papers, 2024 to 2025). "Moreover, cellular transport was also compromised in tumor cells through downregulation of 38 proteins related to vesicle-mediated transport, as well as important proteins involved in vesicle docking involved in exocytosis (such as VPS33B, RAB3D, VAMP3, and SCFD1)." (PMID 39202022, 2024).
nervous system diseases (1 paper, 2022). "Among genes of module-3, NAPA showed the strongest association (60%), SCFD1, and STX5(30–40%) suggesting their possible role in the etiology of nervous system diseases." (PMID 34918006, 2022).
neurodegenerative disease (1 paper, 2023). A disorder of the central nervous system characterized by gradual and progressive loss of neural tissue and neurologic function. "In these neurodegenerative diseases, pathogenetic mechanisms involving SCFD1 have also been identified, leading to a disruption in the mechanism of axonal transport of proteins to the synaptic ending, which is regulated by neurofilaments." (PMID 37894929, 2023).
SCFD1 also shares sentences with these, for which no sentence is quoted: cancer (2 papers); colorectal cancer (2); Parkinson disease (2); schizophrenia (2); Alzheimer disease (1); colon cancer (1); dwarfism (1); glioma (1); heart disease (1); heart failure (1); lymphoma (1); multiple sclerosis (1); Onset (1); prostate carcinoma (1).